ERBB3 (erb-b2 receptor tyrosine kinase 3)
Diseases named in the same sentence as ERBB3 in open-access papers (continued):
Sharing a sentence is not in itself a finding about the gene and the disease.
tumor (continued). "Expression of ERBB3 has, similar to EGFR in our CTC predictor, previously been associated with endocrine therapy resistance when highly expressed in primary tumor tissue." (PMID 26892682, 2016). "Biomarker subtype analysis was performed for NRG1 and ERBB3 in 108 tumor samples (89%; 51/59 in the duligotuzumab arm and 57/62 in the cetuximab arm), both potential indicators of HER3 activity." (PMID 27843803, 2016). "A recent study demonstrated that MM-111 inhibition of ligand-activated ErbB3 phosphorylation is superior to pertuzumab, and that the combination of MM-111 with trastuzumab more effectively inhibits tumor cell growth than pertuzumab plus trastuzumab." (PMID 27596216, 2016). "Comparison of specimens with less than 20% ErbB3-positive cancer cells with those harboring more than 20% ErbB3-positive cells revealed a significant difference in tumor grade, as determined by chi square trend test (p=0.025)." (PMID 27447549, 2016). "By its design, MM-111 blocks the activity of ligand-dependent and ligand-independent ErbB2/ErbB3 complexes in tumor cells, hence, recapitulating the effect of combining trastuzumab and pertuzumab or lapatanib, albeit in a completely different manner." (PMID 27596216, 2016). "The altered RTKs in UC have been reported and associated with tumor cell proliferation and survival, including FGFR3 activation, EGFR amplification, ERBB3 mutation, and ERBB2 mutation or amplification." (PMID 27793038, 2016). "In this study, we investigate the effects of a novel combinatorial strategy based on the use of a HDACi, such as vorinostat or VPA, plus the anti-ErbB3 MoAb, A3, in a set of primary tumor cultures from malignant pleural effusions (MPEs) of NSCLC patients." (PMID 26862736, 2016). "Selectively, in afatinib resistant clones, combined knock down of ERBB3, c-KIT and c-MET caused tumor cell death." (PMID 26934000, 2016). "Tumor growth in ErbB2-amplified cells mainly results from the ligand-independent formation of ErbB2/ErbB3 oncogenic complexes." (PMID 27596216, 2016). "Whereas only a single G1 tumor contained more that 20% ErbB3-positive cells (1/27; 4%), 12% of the G2 tumors (35/299) and 19% of the G3 tumors (14/73) displayed medium-to-strong ErbB3 expression in more than 20% of the cells." (PMID 27447549, 2016). "Afatinib resistant tumor cell killing by [ERBB3 + c-KIT + c-MET] knock down was significantly, though only partially i.e. ∼70% reduction, reduced by knock down of eIF2α, CD95 or Beclin1 (p < 0.05)." (PMID 26934000, 2016). "Another disadvantage of trastuzumab’s working mechanism is that it provides an ErbB3 escape route for the development of tumor resistance." (PMID 27596216, 2016). "This correlation between ErbB3 positivity and increasing tumor grade provides additional support for the contribution of ErbB3 signaling to the dedifferentiation of the intestinal epithelium during tumor progression." (PMID 27447549, 2016). "38.8% (19/49) of tumours had increased ERBB3 expression levels (>2-fold) compared to matched normal tissues." (PMID 26367378, 2015). "The ErbB family members: EGFR, ErbB2, ErbB3, and ErbB4 receptors are established as drivers of many aspects of tumor initiation and progression to metastasis." (PMID 25699077, 2015). "Conditional gene targeting of ErbB3 or p110α in the mammary gland abrogates HER2-mediated tumor formation in genetically engineered mice." (PMID 26637440, 2015). "Most importantly, and as observed in the primary tumours, the expression of ERBB3 and EPHB2 was positively correlated (Pearson correlation test, rho = 0.999, p<0.0001)." (PMID 26367378, 2015).
tumor (continued). "Following co-immunofluorescence and image analysis, the number of P-H3+ cells in the four different cell populations (EPHB2+/ERBB3+; EPHB2+/ERBB3-; EPHB2-/ERBB3+; EPHB2-/ERBB3-) was quantitated (between 100–200 P-H3+ cells per tumour)." (PMID 26367378, 2015). "The positive correlations found at the RNA level between ERBB3 and intestinal stem cell markers prompted us to investigate the potential co-localisation of ERBB3 and intestinal stem cell markers in tumours." (PMID 26367378, 2015). "A possible link of ERBB3 to apoptosis can be deduced from a functional in vivo study wherein deletion of ERBB3 in mouse intestinal epithelium induced tumor-specific cell death." (PMID 25922907, 2015). "Linear regression modelling indicated that ERBB3 expression levels were also significantly higher in stage IV tumours compared to stage I tumours (Coefficient = 1.36, (95% confidence interval (CI) 0.07, 2.64), p = 0.039, data not shown)." (PMID 26367378, 2015). "CD15/FUT4 overexpression is driven by constitutive oncogenic signalling pathways in the tumor cells (innate immune resistance) acting as a novel RAF-MEK-ERK kinase downstream regulator through ERBB3 or FGFR4 activation, respectively." (PMID 26427914, 2015). "Recent investigation has elucidated tumor cell-level mechanisms that account for suboptimal responses to HER2-targeted therapies, including overexpression of EGFR, cMYC, or ERBB3, and mutational loss of PTEN or activation of PI3K." (PMID 25997452, 2015). "First, activation of erbB3 signaling not only confers drug resistance in cancer treatment, but also promotes tumor metastasis." (PMID 24886126, 2014). "In this study, we predicted that ERBB3 is a target of miR-143 and miR-145, which are a cluster of miRNAs that have been reported in many studies to be downregulated and to function as tumor suppressors in most cancers." (PMID 25248370, 2014). "The combination of tumor growth reduction and pERBB3 levels observed in tumor lysates suggests that A5/F4 are capable of blocking ligand mediated ERBB3 signaling in vivo." (PMID 25386657, 2014). "The relationship between low Trop2 expression and elevated ErbB3 activation was also observed in primary HNSCC tumors, and importantly, we demonstrate that Trop2 loss confers sensitivity to ErbB3 antibodies in tumor xenografts derived from HNSCC cells." (PMID 25238142, 2014). "Together, the in vitro and in vivo data indicate that anti-ErbB3 antibodies are likely to have potent anti-tumor properties against cancers that exhibit low Trop2 and high p-ErbB3 expression." (PMID 25238142, 2014). "Elevated expression of erbB3 is frequently observed in various malignancies, where it promotes tumor progression via interactions with other receptor tyrosine kinases (RTKs) due to its lack of or weak intrinsic kinase activity." (PMID 24886126, 2014). "To determine if this is the case, we performed a proof-of principle experiment by evaluating the effects of treatment with the anti-ErbB3 antibody on tumor xenografts derived from control or Trop2 knockdown SCC-1 cells." (PMID 25238142, 2014). "Nonetheless, the molecular basis through which tumor cells often co-express erbB2 and erbB3 remains elusive." (PMID 24886126, 2014). "Increased awareness of erbB3 function in cancer progression, particularly tumor recurrence following drug resistance has several implications for future directions of investigation." (PMID 24886126, 2014). "In this study we demonstrate that an oligoclonal mixture of anti-ERBB3 mAbs is more effective than individual component mAbs at inhibiting tumor cell growth and suggests an approach for more effective downregulation of ERBB3-dependent signaling." (PMID 25386657, 2014). "Elevated levels of Erbb3 pY1325 and p85 pY467 in PyMT tumours were confirmed by Western blot analysis with appropriate phosphospecific antibodies." (PMID 25200860, 2014).
tumor (continued). "It is clear that there is overwhelming evidence to support the importance of erbB3 signaling in cancer progression, particularly in therapeutic resistance followed by tumor recurrence." (PMID 24886126, 2014). "We also provided evidence that restoration of ERBB3 expression can reverse miR-143/145-suppressed cell proliferation and invasion, suggesting that the targeting of ERBB3 is one mechanism by which the miR-143/145 cluster exerts its tumor suppressive function." (PMID 25248370, 2014). "The data suggests that in the setting of ERBB2 amplified cancers, overexpression of ERBB2 leads to constitutive ligand-independent heterodimerization with ERBB3 and activation of downstream signaling events that promote tumor progression." (PMID 25386657, 2014). "By differential expression analysis and reverse engineering we found ERBB3 and its network members to be significantly overrepresented within the r4 tumour subgroup." (PMID 23835063, 2013). "BT474 cells also carry physiologic levels of ErbB1 and ErbB3 and low levels of ErbB4, providing them a suitable model system for investigating the impact of ErbB signalling on tumour cell growth and ErbB2-targeted anti-tumour strategies." (PMID 23308242, 2013). "By expression analysis of histopathology categories (i.e. NBs, GNBs, and GNs) we found the r4 subgroup to show an identical expression profile to GNB/GN types, and overexpression of ErbB3 was also confirmed at the protein level in GN tumours." (PMID 23835063, 2013). "The current study identifies ERBB3 as a clear-cut marker of a GNB/GN-like expression profile, and we suggest a 7-gene expression signature (including ERBB3) as a complement to histopathology analysis of neuroblastic tumours." (PMID 23835063, 2013). "In tumor cells, ErbB2 activates ErbB3, which stimulates several intracellular signaling proteins and pathways, including MAPK, PI3K/Akt and Src kinase." (PMID 23739740, 2013). "The highest enrichment of the ERBB3-network was found in GN tumours, with 18 up-regulated genes out of 38 (p < 0.001)." (PMID 23835063, 2013). "In tumor cells, ErbB2 activates ErbB3 by stimulating several intracellular signaling proteins, such as MAPK, PI3K/Akt and Src kinase." (PMID 23739740, 2013). "The IHC was performed on formalin-fixed and paraffin-embedded (FFPE) tissue slides from four GN and four NB tumours by using antibodies specific for Sox10 ([N-20], Santa Cruz Biotechnology) and ErbB-3 ([RTJ2], Abcam) respectively." (PMID 23835063, 2013). "Although the extent of the role of ErbB3 is emerging, its clinical relevance in different tumours is controversial." (PMID 23835063, 2013). "In these studies, inactivation ErbB1 and ErbB2 receptors restored cell growth by reactivation of ErbB3 and ErbB4 receptor signalling and redirected tumour cell growth from an ERK1/2 to an Akt-dependent mechanism." (PMID 23308242, 2013). "The high ErbB3 expression in GN tumour types was verified at the protein level, and showed mainly expression in the mature ganglion cells." (PMID 23835063, 2013). "ErbB family member genes (ERBB-genes; EGFR, ERBB2, and ERBB3) and 15 previously reported tumour suppressor candidate genes (TS-genes) were next studied by heat maps in all four data sets." (PMID 23835063, 2013). "We conclude that the ERBB-profile (high expression of EGFR, ERBB2 and ERBB3) defines a ganglion-rich neuroblastic tumour sub-set." (PMID 23835063, 2013). "REGN1400 inhibits phosphorylation of ErbB3 and Akt in multiple human tumor cell lines and growth of these cell lines in vitro." (PMID 22889873, 2012). "The expression levels of ERBB3 within ccRCC were inversely correlated with tumor grade and tumor size (R = −0.287, P = 0.009 and R = −0.244, P = 0.027, respectively)." (PMID 22554477, 2012). "In this model TK-A3 significantly slowed down tumor growth, increase time-to-disease progression and downregulated in vivo ErbB3-mediated signaling." (PMID 22889873, 2012).
tumor (continued). "The antibody shows potent inhibition of tumor growth in a broad spectrum of xenograft models in which ErbB3 is activated by its ligand NRG1 or by HER2 overexpression." (PMID 22889873, 2012). "Recent studies have established that the ErbB2/ErbB3/PI3K complex forms the major oncogenic unit in ErbB2 amplified tumour cells, and that sebsequent activation of Akt is the major oncogenic mechanism." (PMID 23202898, 2012). "Recent studies have demonstrated that miR-125 and miR-205 act as tumor suppressors through directly targeting ERBB3." (PMID 23554686, 2011). "In this study we used MM-121, a fully humanised anti-ErbB3 antibody currently under clinical development, which has been shown to be active in other tumour types." (PMID 21792199, 2011). "We have identified the consistent expression of NRG-1 by CAF in the tumour microenvironment and have thoroughly demonstrated that this ligand promotes tumourigenesis through ErbB3/PI3K/AKT activation." (PMID 21792199, 2011). "EGFR belongs to the ErbB family of receptor tyrosine kinases (which also includes ERBB2 and ERBB3) and members of this family have been implicated both in EMT induction, and in tumor progression." (PMID 21816090, 2011). "Following tumour harvest, protein analysis of MM-121-treated xenografts revealed marked inhibition of ErbB3 protein activation and expression with the consequent inhibition of AKT phosphorylation." (PMID 21792199, 2011). "Here, DNA binding activity at gene specific promoters of Xlr, Nr2f1, Zbtb7b, Sprr2i, Ffg18 and ERBB3 was observed with nuclear extracts of transgenic and tumor bearing mice but the overall activity varied considerably with no obvious trend." (PMID 21464922, 2011). "Our results identify ERBB3 as a direct target of miR-148a, and provide direct evidence that miR-148a inhibits tumor angiogenesis through ERBB3 and its downstream signaling molecules." (PMID 23554686, 2011). "Immunohistochemistry of tumour tissues has previously found moderate or strong ERBB3 expression in 11–49%." (PMID 21364580, 2011). "By contrast, Egfr and Erbb3 were detected at all stages of tumor development, and the Egfr mRNA was the most prominently detected of the 4 Erbbs throughout the multistep pathway." (PMID 20975924, 2010). "By forming heterodimers with other members of the EGFR family, c-erbB3 channels erbB signaling through the PI3K/Akt pathway which in turn promotes tumor growth and progression." (PMID 20331873, 2010). "In an early analysis of the data, low ErbB3/HER3 mRNA levels as measured in 122 of the 130 patient archival tumor tissues appeared to predict clinical benefit in the cohort receiving gemcitabine + pertuzumab versus the gemcitabine + placebo group." (PMID 20066160, 2010). "By adding the molecular markers to the base model, we found that the two marker combinations in the tumor tissue were identified as independent predictors: CyclinD1+/ErbB3+ (HR = 0.44, P = 0.034) and Ebp1+/Cyclin D1- (HR = 4.79, P = 0.003)." (PMID 19025630, 2008). "We observed that Ebp1's cytoplasmic expression also correlated strongly with the nuclear expression of Cyclin D1 and ErbB3 in both normal adjacent and tumor tissues." (PMID 19025630, 2008). "Binding of ALM to ErbB2‘+’/ErbB3‘+’ cells mediates inhibition of tumour cell growth in vitro by effectively targeting the therapeutic anti-ErbB3 A5 scFv." (PMID 18841159, 2008). "The anti-ErbB3 A5 scFv is responsible for the majority of the intrinsic anti-tumour activity of ALM." (PMID 18841159, 2008). "Tumours from bitransgenic mice overexpress the myr-Akt1 and ErbB2 transgenes, but there was dramatically less overexpression and phosphorylation of ErbB3, diminished phosphorylation of ErbB2, decreased level of EGFR protein and undetectable ErbB4 protein." (PMID 18700973, 2008). "In fact, expression of the AR, Cyclin D1 and ErbB3 in normal adjacent tissue was found to be more informative than the corresponding tumor tissue in predicting PSA relapse in univariate models." (PMID 19025630, 2008).
tumor (continued). "First, MVM2 cells and MDA-MB-468 were used to approximate normal tissues that express only ErbB2 or only ErbB3, respectively, and BT-474 cells represented ErbB2‘+’/ErbB3‘+’-positive tumours." (PMID 18841159, 2008). "The A5-linker-ML3.9 bs-scFv also exhibits significantly greater in vivo targeting of ErbB2‘+’/ErbB3‘+’ tumours than derivative molecules that contain only one functional arm targeting ErbB2 or ErbB3." (PMID 18841159, 2008). "Previous reports state that specific ErbB heterodimers, i.e., ErbB1/ErbB2 and ErbB2/ErbB3, result in increased tumor growth and cell proliferation." (PMID 16519802, 2006). "Immunohistochemical studies showed cytoplasmic P-Akt and P-MAPK expression in tumor cells with erbB2 and erbB3 co-expression, predominantly a perivascular distribution." (PMID 16168116, 2005). "The ErbB family of receptor tyrosine kinases, consisting of the EGF receptor, ErbB2, ErbB3 and ErbB4, directs a broad range of developmental events and contributes to the malignancy of a number of tumour types." (PMID 14735165, 2004). "ErbB3 is commonly overexpressed in several types of cancer, contributing to tumor progression and dissemination proposedly by promoting cell migration, yet the underlying molecular mechanism and cellular function remain poorly understood likely due to its lack of intrinsic kinase activity." (PMID 41348103, 2026). "The spatial coexpression of CDH1 and ERBB3 was only observed in the core region of the tumor, which may be related to the proliferation of tumor cells." (PMID 41147013, 2025). "To specifically evaluate the role of HER3 in mediating lung colonization independent of primary tumor growth, we performed tail vein injections of each of the three ERBB3 variant cell lines." (PMID 39753722, 2025). "HER3, a pseudokinase member of the EGFR family encoded by ERBB3 gene, plays essential functions in tumor growth despite an absence of intrinsic kinase activity." (PMID 40012003, 2025). "The overexpression of ERBB2 or ERBB3 partially offset the anti-tumor effects of SD." (PMID 39549017, 2024). "The up-regulation of ERBB3 in ARID2-deficient cells indicates that the absence of ARID2 promotes tumor progression through a critical pathway, underscoring its importance in maintaining cellular homeostasis and preventing tumorigenesis." (PMID 39727945, 2024). "Development of drug resistance to ALK-TKI leads to hyperactivation and development of secondary mutations in kinases such as EGFR, ERBB3, it is therefore worth exploring further the combination of ALK-TKI and ERRB inhibitors to overcome any emerge resistance of these tumours." (PMID 39695132, 2024). "In addition, ERBB3 was downregulated in tumor (log2FC = 0.88, adjusted p-value ≤ 0.001), stromal (log2FC = 1.70, adjusted p-value ≤ 0.001), and immune (log2FC = 1.58, adjusted p-value ≤ 0.001) regions of the NR group." (PMID 39135097, 2024). "Moreover, to test if a gene knockout that leads to reduced tumor growth would impact the antitumor effect of the drug combination, we chose to treat ERBB3-KO tumors, which resulted in reduced xenograft tumor growth." (PMID 38194275, 2024). "The downregulation of Met and Erbb3 in the KO tumours, on the other hand, might contribute to this phenotype." (PMID 36933062, 2023). "Furthermore, ERBB3 is significantly upregulated in lymph nodes that have undergone tumor metastasis compared to normal lymph nodes." (PMID 38144565, 2023). "In agreement with this hypothesis, the transcripts of MET and ERBB3 kinases are decreased in the Kmt2c KO tumours compared to the controls." (PMID 36933062, 2023). "The protein exhibits an affinity for ErbB3 in tumor cells and ErbB4 in cardiomyocytes." (PMID 38132657, 2023).